XPO6 (exportin 6)
Description:
Mediates the nuclear export of actin and profilin-actin complexes in somatic cells.
Synonyms: Exp6; KIAA0370; RANBP20; FLJ22519
Tractability: Antibody: its Gene Ontology location is reachable by antibodies, with high confidence. PROTAC: ubiquitination databases record sites on it; its protein half-life has been measured.
Gene: Protein-coding gene on chromosome 16 (28,097,976 to 28,211,976, reverse strand). Ensembl gene ENSG00000169180.
Subcellular location: Nucleus; Cytoplasm
Subcellular location (Human Protein Atlas): Nucleoli; Nucleoplasm; Cytosol; Plasma membrane
Gene Ontology:
Molecular function: nuclear export signal receptor activity; protein binding; small GTPase binding
Biological process: protein export from nucleus; intracellular protein transport
Cellular component: cytosol; nucleolus; nucleoplasm; protein-containing complex; cytoplasm; nucleus
Genetic constraint (gnomAD): Loss-of-function variants: 1 observed, 119.61 expected, observed/expected ratio (o/e) 0.0084, 90% interval 0.002 to 0.04. The upper end of that interval is the gene's LOEUF score, 0.04, which puts it in group 1 of 6, group 1 being the genes least tolerant of losing a copy. Missense variants: 941 observed, 1,390.9 expected, observed/expected ratio (o/e) 0.68, 90% interval 0.64 to 0.71. Synonymous variants: 510 observed, 556.33 expected, observed/expected ratio (o/e) 0.92, 90% interval 0.85 to 0.99.
Homologues: Orthologues: chimpanzee XPO6 (99% identical), macaque XPO6 (99% identical), pig XPO6 (99% identical), mouse Xpo6 (98% identical), rat Xpo6 (98% identical), guinea pig XPO6 (96% identical), dog XPO6 (94% identical), tropical clawed frog xpo6 (81% identical), zebrafish xpo6 (71% identical), Drosophila melanogaster ebo (24% identical).
Diseases named in the same sentence as XPO6 in open-access papers:
XPO6 is named in the same sentence as 9 diseases in open-access papers, as found by Europe PMC text mining. Sharing a sentence is not in itself a finding about the gene and the disease. The quoted sentences say what the papers report.
breast carcinoma (3 papers, 2019 to 2025). "Of note, low XPO6 expression and therefore nuclear actin accumulation correlate with poor survival of breast cancer patients." (PMID 31414556, 2019). "Interestingly the least abundant protein amongst them, XPO6, has previously been reported to be downregulated in human breast cancer." (PMID 39462388, 2024). "Another exportin family member, XPO6, has emerged as a significant factor in various cancers, notably breast cancer." (PMID 39882192, 2025).
prostate carcinoma (3 papers, 2019 to 2023). A carcinoma that arises from epithelial cells of the prostate gland. "XPO6 was overexpressed and associated with metastatic potential and a poor prognosis in prostate cancer tissue." (PMID 31371628, 2019). "As a nucleocytoplasmic transporter, XPO6 expression is closely related to poor prognosis of patients and is a potential prognostic biomarker for prostate cancer." (PMID 34630514, 2021). "In addition, XPO6 was higher in advanced prostate cancer according to N classification, Gleason scores, and targeted molecular therapy or not." (PMID 37243787, 2023). "Although XPO6, one of the Exportin family members, functions in malignant progression of certain types of cancer, its role in prostate cancer (PCa) has not been elucidated." (PMID 37243787, 2023).
amyotrophic lateral sclerosis (1 paper, 2021). Amyotrophic lateral sclerosis (ALS) is a neurodegenerative disease characterized by progressive muscular paralysis reflecting degeneration of motor neurons in the primary motor cortex, corticospinal tracts, brainstem and spinal cord. "It has been recently reported that the subcellular localization of PFN1 is regulated by exportin 6 and amyotrophic lateral sclerosis(ALS)-related PFN1 mutations have cytoplasmic inclusions and decrease of nuclear import suggesting a critical role of nuclear compartment of PFN1." (PMID 33590416, 2021).
cancer (6 papers, 2019 to 2025). A tumor composed of atypical neoplastic, often pleomorphic cells that invade other tissues. "XPO6 is the most recently discovered member of the exportin family and its upregulation is a prevalent cancer-associated event in PCa." (PMID 37243787, 2023). "For example, reducing XPO6 levels in breast cancer cells drives anti-cancer effects via accumulating profilin-1." (PMID 37243787, 2023). "The RASSF1A/RAN/XPO6/nuclear actin pathway is aberrant in cancer cells where RASSF1A expression is lost and correlates with reduced MRTF‐A/SRF activity leading to cell adhesion defects." (PMID 31414556, 2019). "Accumulating evidence implicates XPO6 in cancer progression." (PMID 37243787, 2023). "Nevertheless, our data strongly suggested that increasing nuclear PFN1 by inhibiting XPO6 could be a promising therapeutic approach to sensitize cancer cells, which frequently overexpress XPO640, to replication stress-inducing chemotherapies." (PMID 36319634, 2022). "Furthermore, we provided evidence that Pfn1 undergoes spatial deregulation in a broad range of cancer due to overexpression of its nuclear exporter exportin-6." (PMID 34235154, 2021). "Using two-box analysis of The Cancer Genome Atlas (TCGA) and Genotype-Tissue Expression (GTEx) databases, we compared the expression levels of XPO, including XPO1, CSE1L, XPOT, XPO5, and XPO6, in each tumor and normal tissue." (PMID 39882192, 2025). "The evidence points towards a nononcogene addiction model where cancer cells become reliant on the dysregulated nuclear export processes mediated by exportins like XPO6." (PMID 39882192, 2025).
tumor (4 papers, 2021 to 2025). "Mice experiments were performed to investigate the role of XPO6 in tumor progression and DTX effect in vivo." (PMID 37243787, 2023). "Here, we firstly described that XPO6 functions as a putative tumor-promoter in PCa." (PMID 37243787, 2023). "Functional experiments indicated that XPO6 could promote tumor development and DTX resistance in PCa." (PMID 37243787, 2023). "Experiments were performed to verify whether XPO6 knockdown could inhibit PCa tumor growth and enhance the efficacy of DTX in vivo." (PMID 37243787, 2023).
infection (1 paper, 2020). The state of being infected such as from the introduction of a foreign agent such as serum, vaccine, antigenic substance or organism. "Ad:XPO6 infection also significantly increased basal migration rates and completely prevented the inhibitory effects of forskolin on migration." (PMID 32119877, 2020). "Infection with Ad:XPO6, however, significantly increased basal proliferation rates and rescued proliferation after forskolin treatment to levels that were not significantly different from untreated Ad:Control infected cells." (PMID 32119877, 2020). "However, infection with Ad:XPO6 or Ad:mDIA-CT significantly reduced basal nuclear actin monomer levels and, importantly, completely reversed the forskolin induced increase in nuclear actin monomer levels, detected by DNAse1-Alexa Fluor-594 staining." (PMID 32119877, 2020). "Infection of cells with Ad:IPO9 also significantly increased nuclear actin monomer levels, while infection with Ad:XPO6 or Ad:mDIA-CT significantly decrease basal nuclear actin monomer levels." (PMID 32119877, 2020).
XPO6 also shares sentences with these, for which no sentence is quoted: HIV-1 infection (1 paper); pancreatic cancer (1); parasitemia (1).